TLR2 (toll like receptor 2)
Diseases named in the same sentence as TLR2 in open-access papers (continued):
Sharing a sentence is not in itself a finding about the gene and the disease.
chronic hepatitis B (6 papers, 2013 to 2022). "Expression of TLR2 was identified in the PBMCs of individuals with chronic hepatitis B who had impaired cytokine production." (PMID 35875205, 2022). "One study showed that HBeAg-positive chronic hepatitis B patients have downregulated TLR2 expression on hepatocytes." (PMID 32151000, 2020). "One study showed that HBeAg-positive chronic hepatitis B patients had downregulated TLR2 expression in the hepatocyte plasma membrane." (PMID 32151000, 2020). "Another group reported that over-expression of TLR2/4 on monocytes could modulate the activities of Tregs in chronic hepatitis B patients." (PMID 25654227, 2015). "However, there are no reports of serum TLR2 in HBeAg negative chronic hepatitis B. In this study, the association of serum TLR2 with clinical findings in chronic hepatitis B patients especially in patients with G1896A stop codon mutation has been investigated." (PMID 24187552, 2013). "Additional studies with longitudinal follow-up of subjects are required to determine the precise impact of TLR2 in HBeAg negative chronic hepatitis B." (PMID 24187552, 2013). "Moreover, they showed that the expression of TLR2 on hepatocytes, Kupffer cells, and peripheral monocytes were significantly increased in HBeAg-negative chronic hepatitis B." (PMID 24187552, 2013).
chronic kidney disease (6 papers, 2009 to 2021). Impairment of the renal function secondary to chronic kidney damage persisting for three or more months. "It has also been proposed that SDMA accumulates in high-density lipoprotein (HDL) fraction from patients with chronic kidney disease causing activation of toll like receptor 2 (TLR-2) and enhancing endothelial proinflammatory response." (PMID 31533264, 2019). "It has also been proposed that SDMA accumulates in high-density lipoprotein (HDL) fractions from patients with chronic kidney disease activating the toll like receptor 2 (TLR-2) and enhancing an endothelial proinflammatory response." (PMID 33917744, 2021). "Moreover, whereas TLR2 and TLR4 are over-expressed on monocytes from patients on haemodialysis, the expression of TLR4 has been reported to be reduced on monocytes in patients with chronic kidney disease (CKD) not receiving dialysis." (PMID 30026783, 2018).
dysplasia (6 papers, 2011 to 2022). A usually neoplastic transformation of the cell, associated with altered architectural tissue patterns. "Furthermore, P. anaerobius interacts with TLR2 and TLR4 to increase intracellular levels of reactive oxidative species leading to cell proliferation, intestinal dysplasia, and CRC progression." (PMID 35884445, 2022). "ICC patients also exhibited elevated levels of toll-like receptor 2 (TLR2) when compared with dysplasia and Ctrl HPV+ groups (P ranging from 0.03 to 0.003), but not when compared with Ctrl HPV−." (PMID 32802959, 2020). "No hyperplastic samples showed positive TLR2 staining on keratinocytes, whereas keratinocytes in 64% of cases of carcinoma and 74% of cases of dysplasia were TLR2 positive." (PMID 21179035, 2011).
endotoxemia (6 papers, 2015 to 2025). "Finally, we identified and verified 9 key genes (Cd274, Cxcl1, Cxcl9, Icam1, Ifit2, Isg15, Stat1, Tlr2, and Usp18), and we predicted seven potential drugs for multi-organ damage in LPS-induced endotoxemia." (PMID 33330617, 2020). "In addition, BLP, a pro-inflammatory component of Escherichia coli membrane, stimulates endotoxemia similar to LPS via TLR2." (PMID 28912777, 2017). "During endotoxemia, TLR5 recognizes bacterial flagellin and, together with TLR2, TLR4, and TLR2, mediates immune responses to other exogenous lipoproteins." (PMID 40076851, 2025).
gastric adenocarcinoma (6 papers, 2018 to 2025). "RT-qPCR results indicated that the mRNA expression levels of four hypoxic endoplasmic reticulum stress-related differential genes—NOX4, ANGPT2, CD36, and TLR2—were correlated with our established prognostic risk model in both gastric adenocarcinoma and adjacent normal tissues." (PMID 40061897, 2025). "Notably, increasing expression levels of TLR2, 4, 5, and 9 have been associated with cancer progression from normal gastric mucosa to pre-cancerous lesions, gastric dysplasia, and ultimately to gastric adenocarcinoma." (PMID 40109582, 2025). "In addition, high TLR2 expression common particularly in human intestinal-type gastric adenocarcinoma, was shown to be associated with a certain TLR2-regulated gene profile and poor patient outcomes." (PMID 29467931, 2018). "The most detailed account of carcinoma cell-intrinsic TLR2 function was described in gastric adenocarcinoma cells that expressed high levels of TLR2, resulting in increased ligand-induced cell proliferation and survival independent of inflammation." (PMID 35048056, 2021). "Finally, the pre-incubation of the human gastric adenocarcinoma cell line AGS with blocking antibodies against Toll-like receptor-2 (TLR2), but not TLR4, prevented HIF-1α induction." (PMID 31185594, 2019).
head and neck squamous cell carcinoma (6 papers, 2011 to 2025). A squamous cell carcinoma that arises from any of the following anatomic sites: lip and oral cavity, nasal cavity, paranasal sinuses, pharynx, larynx, and salivary glands. "In head and neck squamous cell carcinoma models, TLR2 agonist including heat-killed S. aureus and synthetic Pam3CSK4 increase PD-L1 expression." (PMID 41008792, 2025). "Beyond innate immune cells, TLR2 signaling by heat-killed Staphylococcus aureus or Pam3CKS4 can upregulate PD-L1 expression in head and neck squamous cell carcinoma (HNSCC) cells." (PMID 37696895, 2023). "TLR-9, TLR-5, TLR-4, TLR-3, TLR-2 and TLR-1 are linked to some clinical parameters of patients afflicted with head and neck squamous cell carcinoma (HNSCC)." (PMID 36224753, 2022). "Treatment of human head and neck squamous cell carcinoma (HNSCC) cells or patient-derived xenografts implanted in immunocompromised mice with the anti-TLR2 monoclonal antibody T2.5 significantly impaired their in vivo growth, suggesting that TLR2 targeting may improve the outcome of HNSCC patients." (PMID 33321934, 2020).
keratitis (6 papers, 2014 to 2024). A corneal disease that is characterized by inflammation of the cornea. "Nevertheless, stimulation of an innate immune response by pathogen-mediated TLR2 activation serves as a primary defense against Staphylococcus aureus-induced keratitis." (PMID 36499260, 2022). "Moreover, in a keratitis model it has been reported that TLR-2 – NOD2 synergism provides an enhanced inflammatory cytokine response to conidia." (PMID 39605324, 2024). "TLR2 activation also upregulates pro-inflammatory cytokines, and therefore, corneal inflammation, as well as tissue damage in rats with Aspergillus fumigatus keratitis." (PMID 36499260, 2022). "There are suggestions that TLR2 plays a role in the induction of an immunopathological response in the cornea since, in mice lacking TLR2, keratitis lesions were significantly diminished." (PMID 25276842, 2014).
latent infection (6 papers, 2010 to 2022). "A large part of the immune evasion by Mtb is based on the persistent or latent infection of macrophages and the TLR-2-dependent down-regulation of antigen presenting function by Mtb in these macrophages." (PMID 24089996, 2013). "In conclusion, the Mtb DosR antigen, Rv2004c might possibly interact with TLR-2 inducing cytokine response to enable the endurance of Mtb in the granulomas during latent infection." (PMID 28694808, 2017). "However, how TLR2 contributes to latent infection with T. gondii remains unclear." (PMID 31404078, 2019). "In contrast, expression of Coronin-1, Sp110 and TLR-2 mRNAs were not significantly different between the patients (group A) and the close contacts with latent infection (group B)." (PMID 20718957, 2010).
myelodysplastic syndrome (6 papers, 2016 to 2021). A clonal hematopoietic disorder characterized by dysplasia and ineffective hematopoiesis in one or more of the hematopoietic cell lines. "In the myelodysplastic syndromes (MDS), inhibition of TLR2 in cultured BM CD34+ cells from patients with lower risk MDS led to increased formation of erythroid colonies." (PMID 33711076, 2021). "OPN-305, a TLR2-specific antibody, has completed clinical trials for myelodysplastic syndrome (NCT02363491 and NCT03337451)." (PMID 31582899, 2019). "The humanized TLR2 mAb OPN-305 can achieve significant blockade of TLR2 inflammatory signaling in response to bacterial stimuli in healthy subjects, and improved overall response rate in patients with myelodysplastic syndromes that had previously failed hypomethylating agent therapy." (PMID 31717860, 2019). "In particular, TLR2 is overexpressed in the neoplastic CD34+ hematopoietic stem and progenitor cells characteristic of the myelodysplastic syndromes (MDS), and its activation induces the production of IL-8 and inhibits their erythroid differentiation." (PMID 33321934, 2020). "Patients with myelodysplastic syndrome (MDS), a hematopoietic stem cell disorder that may lead to cancer, overexpress TLR2 and may benefit from TLR2 inhibition by OPN-305 antibody." (PMID 31695691, 2019). "Even better results in myelodysplastic syndrome were obtained using CX-01 (NCT02995655), which is a heparin derivative working as a TLR2/4 inhibitor (although not specific, as it also impairs the CXCL12/CXCR4 axis)." (PMID 33321934, 2020).
necrotizing enterocolitis (6 papers, 2010 to 2025). Necrotizing enterocolitis (NEC) is a devastating disease that affects mostly the intestine of premature infants. "Oral administration of B. bifidum OLB 6378 to rats activates Toll-like receptor-2 (TLR-2) to reduce apoptosis in the intestinal epithelium in necrotizing enterocolitis, and cell-surface β-glucan/galactan of B. bifidum PRI1 induces regulatory T cells through a partially TLR-2-mediated mechanism." (PMID 34825137, 2021).
non-small cell lung carcinoma (6 papers, 2008 to 2025). A group of at least three distinct histological types of lung cancer, including non-small cell squamous cell carcinoma, adenocarcinoma, and large cell carcinoma. "In one of the studies, lipoteichoic acids from Gram-positive S. aureus were reported to stimulate proliferation of human non-small-cell lung cancer cells by a mechanism involving TLR-2 activation and release of endogenously formed IL-8, suggesting the crucial role of inflammatory mediators." (PMID 33114460, 2020). "For instance, in human non-small cell lung cancer (NSCLC), Annexin A2 (ANXA2) signals through the TLR2/MYD88 axis in neutrophils, inducing ARG1 mRNA expression through amino acid depletion, which in turn inhibits T-cell viability." (PMID 40342932, 2025).
otitis media (6 papers, 2005 to 2021). Inflammation of the anatomical structures of the middle ear, which is most often caused by an infectious process. "On the basis of these results, the authors suggested that TLR2 signaling plays an important role in the effective clearance of bacteria and attenuation of inflammation in Spn-induced otitis media." (PMID 34360632, 2021). "We also investigated the expression levels of Muc5a, Muc5b, Tgf-β1 and Tlr2 genes which have been reported to be involved in the development of otitis media and inflammation." (PMID 22539951, 2012). "Expression of TNF-α and TLR2, which correlates with inflammation in otitis media, was up-regulated in the ears of mutant mice when examined by immunohistochemistry and semi-quantitative RT-PCR." (PMID 21818352, 2011). "In the pathogenesis of chronic obstructive pulmonary diseases and otitis media, to avoid detrimental inflammatory responses in NTHi infection, TLR2 signaling must be tightly regulated." (PMID 17925880, 2007). "In addition, expression of TLR2 was higher in the inflammatory mucosa with otitis media group compared with the normal control group." (PMID 34360632, 2021). "In this study, bacterial clearance was impaired in TLR2−/− mice compared with that in the control group, indicating that TLR2 plays an important role in the regulation of infection in NTHi-induced otitis media." (PMID 34360632, 2021). "The increased expression of TLR2, TLR3 and TLR4 as a consequence of allergen exposure is in line with a previous report demonstrating an increase of TLR2 protein in chronic middle ear inflammation." (PMID 16146574, 2005).
peripheral nerve injury (6 papers, 2011 to 2023). Injury to a peripheral nerve. "Previous studies indicate that activation of sNAMs in the sensory ganglia, after peripheral nerve injury, depends on downstream signaling generated by the activation of TLR2, TLR4, and TLR9." (PMID 37254842, 2023). "After peripheral nerve injury, TLR2 induces the expressions of proinflammatory cytokines in the nerve injury area, then induce the activation and infiltration of macrophages into the nerve injury area, and plays a certain neuroprotective effect." (PMID 36047918, 2022). "In this context, the present work aimed to investigate the influence of TLR2 and TLR4 on regeneration and functional recovery after peripheral nerve injury." (PMID 27222120, 2016). "Up-regulated heterodimer of TLR1/TLR2 upon stimulation and basal high level of TLR4 in both Schwann cells and sciatic nerve imply that TLR2 and TLR4 are crucial to Wallerian degeneration after peripheral nerve injury." (PMID 23984978, 2013).
pertussis (6 papers, 2010 to 2023). A contagious bacterial respiratory infection caused by Bordetella pertussis. "Pertussis OMVs with wild-type LPS predominantly activated TLR2 and TLR4 and were more reactogenic than Bexsero." (PMID 37542099, 2023). "At the antibody level, IgG1 and IgG3 tended to be higher in N. meningitidis OMVs immunized TLR2−/− mice, whereas IgG3 and IgE tended to be higher in TLR2−/− mice immunized with whole cell pertussis vaccine." (PMID 21203418, 2010). "Thus it seems that also for whole cell pertussis vaccine, TLR2 or TLR4 activation has little influence on CD4+ T cell proliferation." (PMID 21203418, 2010). "The N. meningitidis OMV vaccine and whole cell pertussis vaccine both contain LPS and lipoproteins, which activate TLR4 and TLR2 respectively." (PMID 21203418, 2010). "Here we investigated the role of TLR2 and TLR4 in the induction of immune responses in mice after immunization with a N. meningitidis OMV vaccine and a whole cell pertussis vaccine." (PMID 21203418, 2010). "In addition, we observed an increased activation of TLR2 and NOD2 by strains circulating after, compared to before, the introduction of the pertussis vaccines." (PMID 28076445, 2017). "In the present study, we demonstrate that TLR4 signalling by LPS contributes to generation of adaptive immune responses after immunization with N. meningitidis OMVs or whole cell pertussis vaccine, while TLR2 activation was not required." (PMID 21203418, 2010). "Together our data demonstrate that TLR4 activation contributes to the immunogenicity of the N. meningitidis OMV vaccine and the whole cell pertussis vaccine, but that TLR2 activation is not required." (PMID 21203418, 2010). "We conclude that TLR4 activation contributes to the immunogenicity of the N. meningitidis OMV vaccine and the whole cell pertussis vaccine, but that TLR2 activation is not required." (PMID 21203418, 2010). "Furthermore, we observed a significant increase in TLR2 and NOD2, but not TLR4, activation by strains circulating after the introduction of pertussis vaccines." (PMID 28076445, 2017).
Sjogren syndrome (6 papers, 2012 to 2021). An autoimmune disorder in which immune cells attack and destroy the glands that produce tears and saliva. "Finally, stimulation of TLR2 induces the production of IL-23 and IL-17 cytokines from the PBCs of patients affected by Sjogren's syndrome." (PMID 29850627, 2018). "TLR2, TLR3, and TLR4 were strongly expressed on the SGECs of patients with Sjögren syndrome, and TLR2 signaling induces the production of IL-23/IL-17 via IL-6 and signal transducer and activator of transcription (STAT) in the NF-κB pathway in Sjögren syndrome." (PMID 33224145, 2020). "Likewise, stimulation of salivary gland epithelial cells (SGEC) obtained from patients with primary Sjögren's syndrome (pSS) or bronchial epithelial cells with TLR2, 7 and 9 ligands does not induce BAFF transcription and secretion." (PMID 25360821, 2014).
uveitis (6 papers, 2012 to 2022). An inflammatory process affecting a part of or the entire uvea. "In particular, TLR2 and gB1 may have a critical role in the pathogenesis of uveitis, which is associated with high levels of IL-8 in the aqueous humor." (PMID 31487910, 2019). "Besides mycobacterial factors, host factors particularly TLRs have a role to play, as we have seen this in the form of selective migration of T cells in vitreous in TB uveitis with hypo TLR2-9 expression at the inflammatory site." (PMID 30218032, 2018). "In 2013, upregulated expression of TLR2/TLR4 was found in macrophages isolated from BD patients, and that TLR2/TLR4-mediated IL-1β was upregulated in patients with active uveitis when stimulated with peptidoglycan/LPS." (PMID 35359926, 2022). "However, TLR2 and TLR9 stimulation showed lower proliferation of CD4+ Teff cells in non-uveitis TB patients, hinting towards the possible role of mycobacterial factors as immune modulators in patients with IOTB as well." (PMID 30218032, 2018). "However, in contrast to TLR2 and TLR9, the mRNA levels of TLR4 were significantly higher in IOTB (73.72 ± 53.33) as compared to non-uveitis subjects (2.44 ± 1.27) (p = 0.05)." (PMID 30218032, 2018). "We observed significantly lower mRNA levels of TLR2 in cells of vitreous humor in IOTB subjects (0.8 ± 0.32) as compared to non-TB uveitis (176.6 ± 104.1) (p = 0.004) and non-uveitis subjects (2.77 ± 0.92) (p = 0.05)." (PMID 30218032, 2018). "Firstly, the cells in vitreous fluids showed lower expression of TLR2 and TLR9 in IOTB as compared to non-uveitis and non-TB uveitis groups." (PMID 30218032, 2018).
vitamin D deficiency (6 papers, 2013 to 2024). A nutritional condition produced by a deficiency of VITAMIN D in the diet, insufficient production of vitamin D in the skin, inadequate absorption of vitamin D from the diet, or abnormal conversion of vitamin D to its bioactive metabolites. "Results showed that vitamin D deficiency increased pulmonary TLR2, TLR4 and dectin-1 expression at baseline both at mRNA and protein levels." (PMID 24926881, 2014). "We investigated whether vitamin D deficiency affects the expression of TLR2, TLR4, and dectin-1 on AMs at baseline by flow cytometry." (PMID 24926881, 2014). "Thus, vitamin D deficiency caused enhanced up-regulation of TLR2, TLR4 and dectin-1 in the lungs of mice both at baseline and post A. fumigatus challenge." (PMID 24926881, 2014). "Vitamin D deficiency increases the expression of hepatic mRNA levels of TLR-2, TLR-4, and TLR-9 in obese rats; however, calcitriol suppresses the expression of TLR-2 and TLR-4 protein and mRNA in human monocytes and triggers hyporesponsiveness to pathogen-associated molecular patterns." (PMID 23589715, 2013). "Vitamin D deficiency is associated with increased inflammatory markers in diabetics including C-reactive protein (CRP), monocyte toll-like receptor 2 (TLR-2), TLR-4, and nuclear factor-κB (NFκB) expression which might predict increased risk of microvascular complications." (PMID 32467811, 2020).